C19orf53 (chromosome 19 open reading frame 53)
Description:
May have a potential role in hypercalcemia of malignancy.
Synonyms: HSPC023; L10K; Hero11; LYDG10
Tractability: Small molecule: a structure with a bound ligand is known. PROTAC: ubiquitination databases record sites on it; its protein half-life has been measured.
Gene: Protein-coding gene on chromosome 19 (13,774,454 to 13,778,773, forward strand). Ensembl gene ENSG00000104979.
Subcellular location (Human Protein Atlas): Nucleoli; Nucleoplasm
Genetic constraint (gnomAD): Loss-of-function variants: 9 observed, 6.87 expected, observed/expected ratio (o/e) 1.31, 90% interval 0.77 to 1.89. That is too few expected variants to judge how well the gene tolerates losing a copy. Missense variants: 166 observed, 135.77 expected, observed/expected ratio (o/e) 1.22, 90% interval 1.08 to 1.39. Synonymous variants: 68 observed, 53.92 expected, observed/expected ratio (o/e) 1.26, 90% interval 1.04 to 1.54.
Homologues: Orthologues: chimpanzee C19H19orf53 (100% identical), pig C19orf53 (89% identical), dog C19orf53 (83% identical), mouse D8Ertd738e (80% identical), guinea pig C19orf53 (78% identical), rabbit C19orf53 (78% identical), zebrafish zgc:136864 (58% identical), tropical clawed frog c3h19orf53 (57% identical), Caenorhabditis elegans K07F5.15 (23% identical).
Diseases named in the same sentence as C19orf53 in open-access papers:
C19orf53 is named in the same sentence as 13 diseases in open-access papers, as found by Europe PMC text mining. Sharing a sentence is not in itself a finding about the gene and the disease. The quoted sentences say what the papers report.
ischemic stroke (3 papers, 2024 to 2025). A stroke disorder caused by obstruction of blood flow to the brain, due to thrombotic (local blood clot formation) or embolic (due to a blood clot or other material traveling from another site) event. "In our previous studies, we revealed an association between the risk of ischemic stroke and the genes C9orf16, C19orf53, SERBP1, and SERF2 using a population genetics-based approach." (PMID 40459864, 2025). "In our prior research, we investigated the impact of four Hero genes—C9orf16 (Hero9), SERBP1 (Hero45), SERF2 (Hero7), and C19orf53 (Hero11) —on ischemic stroke risk, finding a notable association between these genes and the disease." (PMID 39595169, 2024). "In order to address the involvement of Hero-proteins in the pathobiology of CVDs, we have previously conducted a genetic study exploring the associations of the genes C19orf53, SERBP1, SERF2, and C9orf16 (BBLN) with ischemic stroke." (PMID 40459864, 2025). "The unique chaperone-like properties of C19orf53, discovered in 2020 as a “hero” protein, make it an intriguing subject for research in relation to ischemic stroke (IS)." (PMID 39337941, 2024).
ovarian carcinoma (2 papers, 2020 to 2021). A malignant neoplasm originating from the surface ovarian epithelium. "Leydig cell tumour protein homolog (c19orf53) is associated with various biological pathways, such as rRNA biogenesis, ovarian cancer and replication of Zika virus." (PMID 32784430, 2020). "In another study that used robust Bayesian network modeling, 13 hub genes including ARID1A, C19orf53, CSKN2A1, and COL5A2 signature with a prognostic function in ovarian cancer was established." (PMID 34054929, 2021).
cerebrovascular disease (1 paper, 2024). "The results were supported with a bioinformatic assessment, revealing genome-, epigenome-, and proteome-wide effects of C19orf53 polymorphisms as well as an established link between SNPs in the C19orf53 gene and cerebrovascular disease-related phenotypes." (PMID 39337941, 2024).
Hypercalcemia (1 paper, 2014). An abnormally increased calcium concentration in the blood. "C19orf53 is known to be associated with Leydig cell tumors which are a member of the sex cord-stromal tumor group of ovarian and testicular cancers and it has a potential role in hypercalcemia of malignancy." (PMID 25551281, 2014).
Stroke (1 paper, 2024). Sudden impairment of blood flow to a part of the brain due to occlusion or rupture of an artery to the brain. "This intricate web of correlations underscores the potential involvement of C19orf53 in oxidative stress pathways and its connection to the risk of stroke." (PMID 39337941, 2024). "Here, providing genetic evidence that SNPs rs10104, rs11666524, rs346157, rs346158, and rs2277947 C19orf53 are associated with IS risk, we report that C19orf53 is involved in the pathogenesis of stroke." (PMID 39337941, 2024). "The analysis of transcriptomic profiling data has unveiled a significant correlation between C19orf53 and key genes involved in oxidative stress response, shedding light on its potential role in the risk of stroke." (PMID 39337941, 2024). "This newfound association underscores the implication of C19orf53 in the heat stress response, a pathway of paramount importance in the context of ischemia/reperfusion events and stroke pathogenesis." (PMID 39337941, 2024). "Additionally, to further emphasize C19orf53’s potential impact on the risk of stroke, there exists a significant relationship between C19orf53 and Heat Shock Factor 1 (HSF1) discovered by the authors." (PMID 39337941, 2024).
cancer (1 paper, 2023). A tumor composed of atypical neoplastic, often pleomorphic cells that invade other tissues. "Another subgroup of PPIs presumably perturbed by cancers is characterized by negative or near-zero r-values in cancers and positive r-values of gene co-expression in conditionally normal tissues, for example, C1orf131/EIF3L, C19orf53/APEX1, C1orf198/PPP2R1A and C1orf198/ARHGEF1." (PMID 37373333, 2023).
cardiovascular diseases (1 paper, 2025). "Here, we aimed to perform a bioinformatic analysis of the overall contribution of the tag SNPs of genes C11orf58 (Hero-20), C19orf53 (Hero-11), C9orf16 (Hero-9), C19orf53 (Hero-11), SERBP1 (Hero-45), and SERF2 (Hero-7), encoding the Hero-proteins to cardiovascular diseases." (PMID 40459864, 2025).
C19orf53 also shares sentences with these, for which no sentence is quoted: Obesity (2 papers); Arrhythmia (1); dyslipidemia (1); high blood pressure (1); Leydig cell tumor (1); testicular cancer (1).